IL6 (interleukin 6)
Diseases named in the same sentence as IL6 in open-access papers (continued):
Sharing a sentence is not in itself a finding about the gene and the disease.
tumor (continued). "A positive feedback loop has been reported for A3B and interleukin-6 (IL-6) in HCC cells, suggesting that A3B may thus support the recruitment of myeloid-derived suppressor cells (MDSCs) and tumour-associated macrophages (TAMs) into the tumour microenvironment." (PMID 38535531, 2024). "Thus, this study may explain our predictions for the IL-6 transcripts and support the idea that its expression level in tumor tissues is different from that in the blood of NSCLC patients." (PMID 38103126, 2024). "IL-6 plasma concentrations were also found to markedly increase during exercise, being recognized as an additional factor involved in tumor homing: blockade of training-induced IL- 6 by specific antibodies reduced the inhibitory effect on tumor growth and the infiltration of tumors by NK cells." (PMID 38164270, 2024). "The tumor-associated macrophages (TAMs) in OC-TME are often polarized towards an M2-like, pro-tumorigenic phenotype under the effect of elevated IL6 levels and secrete more IL6 to maintain their immunosuppressive function, aiding in immune evasion and promoting tumor progression." (PMID 39766086, 2024). "Furthermore, p38 MAPK favors BC growth and metastatization by acting on the tumor microenvironment and enhancing tumor vascularization through the increase of several pro-angiogenic cytokines, such as vascular endothelial growth factor A and IL6." (PMID 37979099, 2024). "The downregulated IL-6 pathway in tumor tissues may indicate an immunosuppressive microenvironment." (PMID 38881895, 2024). "This study suggests that IL-6 concentrations before diagnosis may play an important role in long-term prognosis among BC patients, even after adjustment for age at diagnosis, stage of tumour, and BMI." (PMID 39342063, 2024). "Furthermore, VP may partly bypass YAP and target IL-6 directly or via other pathways, as the tumor-inhibitory effects of VP were reported to be YAP-independently." (PMID 37877098, 2023). "Besides, IL-6 could promote the differentiation of Th2 and Th17 cells, thereby tilt anti-tumor immune response to an immunosuppressive response." (PMID 37153543, 2023). "However, in neoplastic diseases, IL-6 may promote tumor growth by supporting the survival of altered cells in a hostile environment." (PMID 36900322, 2023). "In addition, myoferlin knockdown significantly reduced IL-6-mediated tumor growth and metastasis." (PMID 37538852, 2023). "However, unlike in the case of Poly(I:C), when Nexavant is administered, there is enhanced secretion of cytokines, such as IFN-β and IL-6, which may induce a unique tumor microenvironment for improved anti-cancer effect." (PMID 38136298, 2023). "Additionally, CAFs aggravate tumor development by secreting IL-1β, IL-6, and IL-8." (PMID 37990331, 2023). "Therefore, tumor cell-derived IL-6 and PTHrP may play an important role in CAC by activating BAT and/or adipose tissue browning." (PMID 37205195, 2023). "Therefore, the demonstrated decrease in IL-6 levels could justify the significant reduction in the viability of the F3II tumor line treated with the venom compared to the untreated control, which constitutes an unprecedented study for scorpion venoms." (PMID 38137888, 2023). "In addition, there is some evidence that suggests IL-6 concentration could be related to tumour size, recurrence, or disease stage." (PMID 37794245, 2023). "It appears that the effect of IL-6 on EMT may depend on the tumor cell type." (PMID 36814597, 2023). "In addition, CAFs establish immune crosstalk by secreting chemokines and cytokines such as IL-6, TGF-β, and CXCL12, thereby interfering with T cell function and recruiting myeloid-derived suppressor cells (MDSC), regulatory T cells (Treg) and tumor-associated macrophage (TAM)." (PMID 37046312, 2023).
tumor (continued). "In addition, IL-6 has been reported to be one of the critical cytokines for the induction of suppressive immune cell subsets, such as myeloid-derived suppressor cells and Th17, which are known to negatively affect anti-tumor immunity." (PMID 38469154, 2023). "In addition, we found a negative association between LOC339059 and IL-6 expression in cancer tissues, suggesting an interrelation between them inside human tumor tissues." (PMID 38001573, 2023). "In addition, recent evidence has shown that pentoxifylline inhibits tumor growth and angiogenesis by inhibiting IL-6 secretion and VEGF–VEGFR2 signaling via the STAT3 signaling pathway, which is associated with the non-classical proangiogenic stem cell factor (SCF)." (PMID 37190108, 2023). "On the basis that I-TAC, C5/C5a, IL-6, CD54, and IL-27 are the cytokines related to the immune system, we conclude that the KUP system acts as ROS photogenerators and induces the immune activity to control the release of cytokines, which cause the tumor eradication." (PMID 36932086, 2023). "IL-6 and other proinflammatory cytokines may be present in tumor derived exosomes." (PMID 36672227, 2023). "IL-6/IL-6R inhibition may be an effective strategy to inhibit tumor progression and metastasis." (PMID 37208766, 2023). "Thus, aberrant XIST expression in SUM159 BCCs may serve as nuclear sinks to sequester/antagonize tumor suppressive miRNAs such as let-7a-2-3p to regulate tumor proinflammatory (i.e., IL-6) signaling." (PMID 36922677, 2023). "In inflammatory responses to the tumor or from the tumor itself, several inflammatory mediators were discharged, containing interleukin-1(IL-1), IL-6, necrosis factor, and acute phase reactants, which might promote albumin escape from capillaries and modulate the production of albumin in the liver." (PMID 36950094, 2023). "Moreover, the mRNA level of IL-6 in MDSCs from the spleen after cryo-thermal therapy was significantly upregulated at both the early (7 d) and late (21 d) stages compared with that in tumor-bearing mice." (PMID 37108179, 2023). "Therefore, in the current study, we investigated the amount of F. nucleatum and its relationship with the expression of inflammatory genes (TLR-2, TLR-4, TNF-α, IL-6, IL-10, IL-12β, and IL-17) and miRNAs (miR-21, and miR-31) in tumor and adjacent normal tissue of Iranian CRC patients." (PMID 38075864, 2023). "Together, these findings suggest that the therapeutic spectrum of these IL-6-signaling targeting agents may be extended to preventing tumor metastasis, although the therapeutic use of these biological agents for cancer intervention remains to be evaluated and optimized." (PMID 37047623, 2023). "Moreover, elevated levels of pro-inflammatory factors TNF-α, IL-1β, and IL-6 in the serum of LLC tumor-bearing mice could be detected by ELISA assay, whereas UA could obviously reduce the concentration of inflammatory factors in a dose-dependent manner." (PMID 37190306, 2023). "However, IL-6 is also a pleiotropic proinflammatory cytokine that reflects a negative prognosis in cancer patients, and prolonged signaling can lead to T cell dysfunction, thereby suppressing anti-tumor immune responses." (PMID 37741983, 2023). "Furthermore, we found that the levels of pro-inflammatory factors TNF-α, IL-1β, and IL-6 in the serum of LLC tumor-bearing mice lowered by UA could be raised by Ex-527 treatment." (PMID 37190306, 2023). "In addition, the ROS may also induce the secretion of extracellular carriers and further enhance the production of IFN and IL-6 in macrophages, thereby inhibiting the immune response in the tumor microenvironment." (PMID 38274828, 2023). "Likewise, recent findings demonstrated that BMP4 overexpression in LCs amplifies the generation of M2-like macrophages with protumor characteristics, evidenced by a decreased TNFα/IL-10 expression ratio and increased levels of CCL2 and IL-6, promoting tumor progression." (PMID 38299154, 2023).
tumor (continued). "Moreover, IL-6/JAK/STAT3 inhibits the anti-tumour immune response." (PMID 37753372, 2023). "Besides, tumor-derived interleukin 6 (IL-6) supports IL23-mediated Th17 cell expansion." (PMID 37234990, 2023). "Finally, we also found that FH-deficient tumour tissue exhibited increased levels of interleukin-6 (IL-6), but not IL-10, confirming the presence of an inflammatory milieu in these tumour tissues." (PMID 36890229, 2023). "Additionally, blocking IL-6 signaling on tumor cells can overcome this resistance." (PMID 37990309, 2023). "Furthermore, tumor-derived TNF-α might lead to an additional increase in plasma IL-6 by its release from ECs." (PMID 37222464, 2023). "Our studies suggest that administration of IL-6 or G-CSF signaling inhibitors in the peri-chemotherapy period (at least in patients who might be expected to have a surge of IL-6 or G-CSF levels due to chemotherapy) might decrease tumor recurrence and improve survival outcomes." (PMID 37699010, 2023). "Thus, by promoting progenitor/memory-like properties, IL-6 may support the longevity of anti-tumor CTLs but nevertheless limit ICI efficacy by impairing their development into effector cells." (PMID 36599350, 2023). "Therefore, the expression of Il6, Nos2, Ccl2, Spp1, Tnf, Acat2, Aox1, Crem, Gls2, Per3, Pink1, Txnip, and Ypel3 was examined in acidosis upon simultaneous transfection with microRNA mimics or antagomirs in two tumor lines in vitro and in vivo." (PMID 38069241, 2023). "In tumor cells only IL-6 and IL-8 could be measured after 24 h." (PMID 36903253, 2023). "IL-6 is a major proinflammatory cytokine that can mediate tumor–host interactions through multiple mechanisms including the recruitment and activation of macrophages, deactivation of macrophage tumor cytotoxicity, effects on other immune cells, and promotion of angiogenesis." (PMID 37509362, 2023). "Besides acting on plasma cells directly at the level of growth inhibition and induction of apoptosis, it also reduces the production of tumor-promoting interleukins (most notably IL-6) by osteoclasts and macrophages in the bone marrow, where plasma cells home and form the tumor lesion." (PMID 36592287, 2023). "On the other hand, inflammatory cells play a role in promoting tumor development by secreting a variety of inflammatory cytokines and chemokines, as well as proangiogenic factors (e.g., tumor necrosis factor, interleukin-1, interleukin-6, and vascular endothelial growth factor)." (PMID 35249158, 2023). "Furthermore, these findings highlight the crucial role of ERK5 in IL-6 production by tumor cells." (PMID 37601096, 2023). "In addition to the inflammatory markers and tumor markers, the pro-inflammatory cytokines, IL-1β and IL-6, and TNF-α serum detection could play an important role in diagnosis and also in prognosis, although their detection incurs increased costs." (PMID 38137862, 2023). "However, IL-6 blockade has also provided anti-tumor benefits in multiple preclinical models." (PMID 37461742, 2023). "However, like IL-6, TNFα can also directly bind tumor cells to enhance survival and proliferation." (PMID 37461742, 2023). "Additionally, IL-6 is involved in the survival and progression of tumor cells." (PMID 37208766, 2023). "Elevated IL‐4 and miR‐324‐5p levels in tumour microenvironment caused a decreased expression level of CUEDC2 in tumour‐associated macrophages, which resulted in excessive levels of proinflammatory cytokines, such as TNF‐α and IL‐6, and linked with both colitis and colon carcinogenesis." (PMID 37138536, 2023).
tumor (continued). "Alternatively, the expression of PD-L1 may depend on inflammatory signals, cytokines, and metabolites (i.e., IFN-α, TNF-α, IL-6) arising from the tumor cells themselves or from the TILs, the antigen-presenting cells (APC), and the tumor-associated macrophages (TAMs)." (PMID 37377735, 2023). "The interaction between CD40 and its ligand CD40L can cause tumor growth inhibition due to immunologic mechanisms and apoptosis induction; alternatively, it may promote tumor growth through the action of cytokines and growth factors, such as interleukin 6 and vascular endothelial growth factor." (PMID 37970926, 2023). "The 4-culture tumor spheroids were characterized by spatial proximity of PSC and monocytes to the endothelial cells and a cytokine signature with increased concentrations of CXCL10, CCL2, and IL-6, which have been observed in PDAC patients and associated with poor survival." (PMID 37519820, 2023). "Activation of SRC in tumor-associated macrophages is induced by tumor-derived cytokines and chemokines (e.g., TNF, MIP, SDF-1), which amplify the production of inflammatory cytokines (e.g., TNF, IL1β, IL6) to reciprocally activate SRC in a feed-forward loop and promote PDAC progression." (PMID 37120696, 2023). "Therefore, the IL-6/STAT3 signaling pathway is involved in the process of tumor cell resistance." (PMID 37990309, 2023). "Therefore, the suppression of macrophage polarization into M2-like TAMs in the tumor microenvironment may inhibit TAM-derived IL-6-induced cancer stemness." (PMID 36838713, 2023). "Therefore, high levels of IL-6 should reflect the tumor size." (PMID 37173873, 2023). "However, a chronically elevated level of IL-6 promotes tumor cell survival, is a poor prognostic factor, and may indicate the occurrence of irAEs during ICIs treatment." (PMID 36981837, 2023). "Other protumorigenic cytokines, such as GROα/β/γ, IL-8, and IL-6, are known to be secreted by cancer and stromal cells, whereas IL-2 and IL-3 are secreted from activated T cells to regulate the activity and maturation of immune cells to be able to eliminate tumor cells." (PMID 37759302, 2023). "Furthermore, since SC144 is a gp130 inhibitor and IL-6/gp130 axis is important in both polarization of TAMs and cancer cell growth, we investigated whether IL-6 plays an important role in the anti-tumor efficacy of SC144@HABN + anti-PD-L1 combo therapy." (PMID 37553327, 2023). "Furthermore, the tumor immunosuppression was suggested to be induced by IL-6 via HIF1α activation." (PMID 36764954, 2023). "In HCC cell lines Hep3B and MHCC97H, CBS inhibits tumour growth by regulating apoptosis‐related proteins (cleaved Caspase‐3 and Bcl‐3) and inhibiting the transcription of paired related homeobox 2 by interleukin‐ 6 (IL‐6), which negatively regulates the expression of STAT3." (PMID 36929586, 2023). "Inhibition of IL-6/JAK/STAT3 signaling can also affect the tumor microenvironment and has implications for antitumor immunity; therefore, determining whether co-targeting of immune checkpoints and the IL-6/JAK/STAT3 signaling pathway mightbe beneficial is important." (PMID 37720284, 2023). "Therefore, therapies targeting TTC13 as well as IL6-JAK-STAT3 signaling pathway may benefit ccRCC patients by simultaneously suppressing tumor cell growth and stimulating anti-tumor immunity." (PMID 37927783, 2023). "Moreover, upon SKI-II treatment, we observed a significant downregulation of Arg1 expression in the RAW264.7 cells co-cultured with all the tumor cell lines tested, accompanied by increased gene expression of the M1 marker Tnfα and IL-6 cytokine level in the cell-free supernatant of RAW264.7 cells." (PMID 36672428, 2023). "However, our study reveals a critical role for the IL-6/STAT3/miR-214 axis during tumor progression which could be useful in clinical interventions." (PMID 36639824, 2023).
tumor (continued). "In addition to DNA methylation, IL-6, a potent inducer in tumor aggression and MDSCs expansion, could alter RNA methylation in MDSCs to mediate its function." (PMID 37273004, 2023). "The pro-inflammatory cytokine IL-6 might impair anti-tumor immunity through multi-aspect." (PMID 37153543, 2023). "We speculate that the reduced IL‐6 expression may account for anti‐tumour effects in KO mice." (PMID 36419386, 2023). "However, the downregulation of the expression of PFKFB3 may explain the biological effect of the downregulation of tumor invasion and proliferation by sorafenib despite the upregulation of IL-6 at this time." (PMID 37476196, 2023). "In addition, IL-6 could also promote tumor cell survival, growth, proliferation, transformation, invasion, and migration by upregulating TGF-β and activating the STAT3 and HGF/c-MET pathways." (PMID 36831664, 2023). "Furthermore, fruquintinib can correct the immune escape microenvironment of tumor cells, mainly by inhibiting PD-L1 expression, inhibiting tumor release of inflammatory factors and immunosuppressive factors such as IL6/IL-10/VEGFR, and inhibiting bone marrow-derived suppressor cells." (PMID 36969012, 2023). "Moreover, IL-6 secreted by CAFs has a tumor-promoting effect in highly invasive tumors." (PMID 37666813, 2023). "Moreover, especially when incomplete, locoregional treatments can also induce immunosuppressive factors (such as IL-6, VEGF, HIF-1α, TGF-β, PD-1 and PD-L1), stimulate the accumulation of Tregs in the tumor and cause lymphopenia, leading to tumor progression in the end." (PMID 37239941, 2023). "As ALDH- BCCs constitute the majority of tumor cells in the tumor mass, these data suggest that loss of XIST in BCCs significantly reduced the production of proinflammatory cytokine IL-6 and IL-8 in the tumor milieu, which may be responsible for the impaired CSC activities." (PMID 36922677, 2023). "In addition, IL-6 and IL-27 are also important cytokines that upregulate co-inhibitory signals on tumor-infiltrating T cells, correlating with T cell exhaustion in both human and mouse tumor models." (PMID 37398674, 2023). "Similarly, CAF shed GMCSF and IL6, which both promote the pro-tumor TAM and cancer invasiveness." (PMID 38035101, 2023). "Additionally, the level of IL-6 was measured to evaluate the potential tumor malignancy in the conditioned media treated with radiotherapy because we previously reported that IL-6 is the most significantly altered humoral factor when normal fibroblasts transform into CAFs." (PMID 37296933, 2023). "Therefore, immunotherapy targeting IL-6 is a potential target for tumor treatment via TANs." (PMID 36225938, 2022). "Moreover, IL-6 production may enhance mucosal inflammation via T cell activation, providing a link between inflammation and tumour growth." (PMID 35793807, 2022). "The tumor may also activate osteoclasts through the production of IL-6, IL-11 or IL-1β." (PMID 35884563, 2022). "Therefore, IL-6 is the key substance in chronic inflammation and tumor progression." (PMID 36291659, 2022). "Importantly, rituximab itself may induce tumor cells to produce IL-6 and consequently induce T-regulatory cells (Tregs) to secrete IL-17, which leads to tumor growth and rituximab resistance in DLBCL patients." (PMID 35163421, 2022). "Although high IL6 expression is thought to have a tumor-promoting effect in many tumors, IL6 blockade therapy may exacerbate tumor growth because high IL6 expression increases the expression of cytokine signaling 3, which is required for the maintenance of antitumor M1 macrophage function." (PMID 36506508, 2022). "Moreover, lncRNA Olfr29-ps1 can be upregulated by IL6, which can be a potential anti-tumor target." (PMID 35222443, 2022). "Thus, IL-17A and IL-6 cytokines have an inverse correlation in tumor immunology." (PMID 37529004, 2022). "CAFs could affect intra tumoral CD8+ and FoxP3+ T cells via IL-6 in tumor microenvironment." (PMID 35924148, 2022).